SEMA4D (semaphorin 4D)
Diseases named in the same sentence as SEMA4D in open-access papers (continued):
Sharing a sentence is not in itself a finding about the gene and the disease.
tumor (continued). "Furthermore, the expression level of circ_NRIP1 was knocked down in xenograft tumor tissues, as accompanied with higher miR-595 and lower SEMA4D." (PMID 33957921, 2021). "A decrease in PMN-MDSC recruitment has been observed after the use of Sema4D mAb to treat murine oral cancer 1 (MOC1); this phenomenon is associated with decreased expression of MAPK-dependent chemokines such as CXCL1, 2, and 5 in tumor cells." (PMID 34403220, 2021). "Sema4D secreted by cancer cells was also found to regulate the tumor microenvironment, promoting the recruitment from the bone marrow of myeloid-derived suppressor cells 78, and the formation of a dense fibrotic peri-tumoral stroma 79, both hindering anti-cancer immune response." (PMID 33537086, 2021). "This biological association between Sema4D and HIS-IE raises the question whether Sema4D is of potential use as a predictive biomarker for the underlying tumor inflammatory stromal subtype?" (PMID 33776991, 2021). "This study identifies the inhibitory effects of SEMA4D gene silencing on tumor progression." (PMID 34337054, 2021). "Sema4D is an immune biomarker that may be informative of the global immune contexture and hence facilitates visualization of all leukocytes in the tumor core and peritumoral stroma." (PMID 33776991, 2021). "Emerging evidence has shown that Sema4D may represent an alternative pro-angiogenic factor produced by tumor cells in response to anti-VEGF therapy, responsible for resistance to therapy." (PMID 33537086, 2021). "Luckily, our data supported the upregulation of SEMA4D in ESCC tumor tissues and cells." (PMID 33957921, 2021). "Additionally, the function of Sema4D in promoting tumor progression has been confirmed in various malignant tumors in human and animal models, and associated with a poor prognosis." (PMID 34403220, 2021). "Immune-related semaphorins such as SEMA3A, SEMA4A and SEMA4D may also affect tumor progression via the influencing the immune system." (PMID 31205625, 2019). "Because all 6 studies assessed SEMA4D expression from tumor tissue by immunohistochemistry staining and reported the HRs/RRs, IHC group, tissue group and reported HRs/RRs group had a same result as the total DFS/PFS/RFS analysis (HR = 1.59, 95%CI: 1.27–1.98, P < .001)." (PMID 30762724, 2019). "STRING network analysis show that Sema4D interacts with the tumorigenesis-associated protein MET, and that it may have roles in multiple processes such as apoptosis during tumor formation and immune functions in chickens." (PMID 31394878, 2019). "Although SEMA4D activates anti-tumor immune responses that may repress tumor growth, it also potentiates angiogenesis and tumor growth." (PMID 31205625, 2019). "SEMA4D expression in the tumor microenvironment has been shown to promote tumor progression." (PMID 30658382, 2019). "The expression of SEMA4D is mainly related with tumor aggressiveness and poor outcome." (PMID 31205625, 2019). "Sema4D is expressed on tumor cells that colonize bone, while cells of the microenvironment other than osteoclasts may also express Sema4D." (PMID 29971044, 2018). "While other semaphorins such as Sema3B and 3F are tumor suppressors, Sema4D promotes tumor growth." (PMID 29971044, 2018). "Whether the Sema4D+ve/high TAIs subtype is an early or late event in the progression of the disease, or if the inflammatory profile of Sema4D+ve/high TAIs is different between several stages of the tumor is yet to be determined." (PMID 29541402, 2018). "To determine whether Sema4D has a role in modulating the peri-tumoral stroma, we examined the tumor microenvironment in all the provided specimens in terms of inflammation and stromal density." (PMID 29541402, 2018). "Since tumor cells with high Sema4D also have high motility and invasiveness and Sema4D promotes angiogenesis, Sema4D could contribute to metastasis at both at the primary tumor site and distant sites." (PMID 29971044, 2018).
tumor (continued). "Sema4D may also be a biomarker for tumor angiogenesis, since its expression in ovarian cancer correlates with HIF-1, VEGF, and poor prognosis." (PMID 29971044, 2018). "Combination treatment of anti-SEMA4D with anti-LAG3 or epigenetic modulator entinostat resulted in maximal tumor growth delay and 90% CR (p<0.0001).Pepinemab treatment was well tolerated in a Phase I trial in patients with advanced refractory solid tumors (NCT01313065)." (PMID 30400822, 2018). "In addition, tumor-secreted Sema4D increases endothelial expression of platelet-derived growth factor-B and angiopoietin-like protein 4, which promote endothelial proliferation and vascular permeability." (PMID 29971044, 2018). "The fact that Sema4D is upregulated in tumor tissue as well as in autoimmune and allergic conditions, renders inhibition of Sema4D very promising, not only for immunotherapy resistant patients, but also for potential taming of the immune system, to decrease toxic immunotherapy effects." (PMID 29541402, 2018). "The two tumor subtypes observed in this study, according to Sema4D distribution: Sema4D+ve/high." (PMID 29541402, 2018). "A study on tumor-induced angiogenesis showed that Sema4D may function as a direct inducer of endothelial cell migration to promote neovascularization instead of promoting endothelial cell growth like VEGF." (PMID 30405423, 2018). "In addition to direct proliferative actions in cancer cells, Sema4D/Plexin-B1 abnormalities within the tumor niche support cancer progression by promoting angiogenesis." (PMID 29971044, 2018). "Interestingly, R-Ras, whose activity is downregulated during the signal transduction of Sema4D to PlexinBl, also functions to inhibit intimal growth and tumor angiogenesis." (PMID 30405423, 2018). "The current study presents Sema4D expressed by HNSCC tumor cells, as a biomarker for dense fibrotic peri-tumoral stroma, and presents a novel role for Sema4D in modulating the tumor microenvironment through upregulation of ECM collagen production by fibroblasts, and TGF-β1 by tumor cells." (PMID 29541402, 2018). "Tumor cells increase their Sema4D expression as an escape mechanism from anti-VEGF treatment." (PMID 29971044, 2018). "Sema4D then cooperates with VEGF to promote tumor growth and vascularity." (PMID 29971044, 2018). "Also, the endothelial ANGPTL4 secretion induced by tumor-released semaphorin 4D (SEMA4D) has been shown to modulate vascular permeability." (PMID 28182091, 2017). "Above all, PlexinB1 receptors have a high affinity for Sema4D, and contribute to tumor progression." (PMID 27456345, 2016). "It has recently been hypothesized that Sema4D is involved in the regulation of the immune response in the tumor microenvironment." (PMID 27456345, 2016). "However, this seems to differ between tumor type with a tumor-suppressor effect mainly noted in ER-positive breast cancer and melanoma, were binding of Sema4D to PlexinB1 leads to a decrease in cMET phosphorylation." (PMID 25815459, 2015). "In addition, an important role of SEMA4D-Plexin-B1 interaction in regulating different aspects leading to tumor progression, including invasive growth and angiogenesis, is well established." (PMID 25193853, 2014). "As reviewed by Ch’ng and Kumanogoh, several studies have described a role for Sema4D and plexin-B1 in tumor progression, including soft tissue sarcomas, B-cell chronic lymphocytic leukemia, renal cell carcinoma, breast and ovarian carcinomas, prostate adenocarcinoma, and pancreatic cancer." (PMID 23741311, 2013). "When these cells are activated, Sema4D is cleaved proteolytically, generating a biologically active 120-kDa fragment (soluble Sema4D) capable of targeting receptors on platelets, B-cells, endothelial cells and tumor cells." (PMID 23741311, 2013). "We expect that SEMA4D may serve as a reliable tool for early and accurate prediction of tumor recurrence and may be a potential therapeutic target for EOC patients." (PMID 23202951, 2012).
tumor (continued). "Also, the transmembranous semaphorin SEMA4D has recently become a focus of intensive research owing to its capacity to induce tumour cell invasiveness and angiogenesis." (PMID 18781179, 2008). "In addition, its ligand Sema4D is a potent angiogenetic factor, possibly involved in tumour induced angiogenesis." (PMID 17519029, 2007). "However, the role of the PLXNB1/SEMA4D axis in tumours has been elucidated by several studies." (PMID 39443302, 2024). "The source of Sema4D may vary across tumors; in some cases, tumor-associated macrophages, rather than the tumor cells themselves, are the primary producers." (PMID 39769452, 2024). "Activation of Plexin-B1 on endothelial cells by Sema4D which is expressed by tumor cells, promotes angiogenesis; therefore, whole-body knockout of Plexin-B1 in our mouse models would inhibit Sema4D-induced angiogenesis and this may contribute to the decrease in metastasis observed." (PMID 36936664, 2023). "Besides, there still are some other pathological processes mediated by this combination of the Semaphorin family and plexin family, such as that semaphorin-4D (Sema4D) induce tumor angiogenesis and vascular maturation by binding to the plexin B1 receptor on endothelial cells." (PMID 36900158, 2023). "However, understanding the role of SEMA4D in the tumor microenvironment (TME) is limited." (PMID 37287907, 2023). "Thus, instead of interfering with the immune response by affecting tumor neoantigenesis, SEMA4D may lead to immunosuppression mainly by interfering with immune checkpoints in the microenvironment, affecting the effector function of T cells against tumor cells." (PMID 37287907, 2023). "Another potential therapeutic target that may affect MDSCs is semaphorin 4D (Sema4D), a cytokine expressed by several epithelial malignancies and known to induce tumor angiogenesis produced by MDSC resulting in suppression of T-cell proliferation and IFN-γ production." (PMID 35784290, 2022). "Sema4D-positive tumor cells were associated with noninflamed dense stroma." (PMID 36338570, 2022). "It has been suggested in studies that when Sema4D antibodies are combined with immune checkpoint inhibitors, such as the anti-Sema4D antibody Pepinemab, and combined with the immune checkpoint inhibitor PD-L1 mAb Avelumab, they can enhance T-cell activity, thus persistently inhibiting tumor growth." (PMID 36713527, 2022). "Moreover, due to their distribution in diverse cell types in the tumor microenvironment, the detection of Sema4D and its receptor might reflect the representation of other components beyond cancer cells." (PMID 33537086, 2021). "Notably, TAM-derived SEMA4D is critical for tumor angiogenesis and pericytes recruitment." (PMID 30658382, 2019). "The SEMA4D-mediated immunosuppression may play an essential role in the tumor development." (PMID 31205625, 2019). "Also binding of Sema4D to its high affinity receptor Plexin-B1, was shown to mediate downstream activation of RhoA and subsequent microtubule organization enhancing cellular motility and tumor invasion, correlating with poor prognosis." (PMID 29541402, 2018). "Finally, as SEMA4D is a novel prognostic indicator in Group 3 and Group 4 patients, is associated with a decrease in self‐renewal, and growth and is an upstream regulator of RHO activity, we evaluated the effect of this candidate gene on tumor growth in vivo." (PMID 29377567, 2018). "Sema4D/Plexin-B1 responses may vary among different cell lines of the same tumor type." (PMID 29971044, 2018). "The dense fibrotic peri-tumoral stroma observed in the current work, demonstrating collagen I and III, with Sema4D+ve/high HNSCC tumor cells, in addition to the role for Sema4D in induction of collagen deposition by fibroblasts, reveals another prospective by which Sema4D induces immune suppression." (PMID 29541402, 2018).
tumor (continued). "The dual nature of Sema4D between pro and antitumor action may depend on subsets of immune cells in the tumor niche, which in turn may depend on the plasticity of macrophages and T cells within the tumor." (PMID 29971044, 2018). "Therefore, we speculate that SEMA4D inhibition might offer a promising target for tumor anti-angiogenesis therapy and prevention of metastatic progression and invasion in EOC." (PMID 23202951, 2012). "In addition, induction of angiogenesis by tumor cells was made possible by proteolytic cleavage of this membrane-bound Sema4D from the tumor cell surface, releasing its soluble form and thereby permitting Sema4D to act on local as well as distant tumor microenvironments." (PMID 20858260, 2010). "In tumor-associated macrophages, although the lack of Sema4D itself did not alter the differentiation and activation capabilities as well as the cytokine production profile, a significantly lower number of tumor-associated macrophages was observed in the tumor microenvironment." (PMID 20858260, 2010). "Furthermore, it was proposed that PlexinB1 expressed by endothelial cells may mediate the pro-angiogenic activity of Sema4D released by tumour cells." (PMID 17519029, 2007). "The impact of Sema4D on VM was mediated through the RhoA/ROCK pathway, which governs tumor cell plasticity and migration." (PMID 38375479, 2024). "In summary, this study provides new insights into the role of the PLXNB1/SEMA4D axis in LM development of CRC, as well as providing a more comprehensive understanding of the immunological characteristics of tumour metastasis." (PMID 39443302, 2024). "Semaphorin 4D (Sema4D; also known as CD100) is another mediator of BM shown to promote the transmigration of circulating tumor cells across the BBB." (PMID 37190188, 2023). "We further verified the overexpression of SEMA4D in tumor and its distribution in TME by immunohistochemistry, RT-qPCR and flow cytometry, and confirmed that decreased expression of SEMA4D can lead to recovery of T cell exhaustion." (PMID 37287907, 2023). "The soluble cleaved form of sema4D was found to promote epithelial-mesenchymal transition (EMT) and, consequently, tumor cells metastasis via plexin-B1." (PMID 37627074, 2023). "As SEMA4D is highly expressed in HNSCC cells, Basile and colleagues silenced SEMA4D gene expression and found that vascularization of HNSCC tumor xenografts was dramatically decreased." (PMID 37504226, 2023). "The SEMA4D and SEMA4F expression was seen in 100% of the human tumor cells, albeit at low intensity." (PMID 35570846, 2022). "IHC scores of Plexin-B2, SEMA4C, SEMA4D, and SEMA4 were calculated based on the percentage of stain present and the stain intensity of tumor cells in the tumor tissues of human patients and mouse models." (PMID 35570846, 2022). "In the presence of anti-Sema4D antibodies, macrophages secrete SDF1, which leads to stronger tumor cell migration by binding to CXCR4 receptor." (PMID 35155237, 2022). "The combination of the Sema4D mAb and anti-PD1 in MOC1 or Lewis lung carcinoma mouse models suppresses tumor growth and significantly improves survival in both models." (PMID 34403220, 2021). "Once in the tumor, TAMs secrete pro-angiogenic factors such as VEGF-A, TGF-β, fibroblast growth factor-2 (FGF-2), CCL18, semaphorin 4D (Sema4D), adrenomedullin (ADM), and placental growth factor (PlGF)." (PMID 33783686, 2021). "To investigate if Sema4D mediates TGF-β1 production, through binding to its receptor Plexin-B1 on tumor cells, we used siRNA system for transient silencing of Plexin-B1 in several HNSCC cell lines of the oral tongue." (PMID 29541402, 2018). "Tumor cells were generally Sema4D-ve/low in stage I and II, Sema4D+ve/high in stage III and Sema4D-ve/low in stage IV." (PMID 29541402, 2018). "We observed that Sema4D is positive in cells bearing the monocytic/macrophage marker CD163, indicating that Sema4D is positive in the macrophage lineage of the tumor microenvironment." (PMID 29541402, 2018).
tumor (continued). "Single agent anti-SEMA4D shifted the balance of immune activity in the TME and significantly delayed tumor growth, but induced a relatively low frequency of complete tumor regression in some preclinical models." (PMID 28649381, 2017). "Expressed on tumor cells and immune cells at the invasive tumor margin, SEMA4D inhibits the migration of antigen presenting cells (APC) and prevents immune cells from infiltrating the tumor." (PMID 28649381, 2017). "Silencing Sema4D expression by lentiviral shRNA dramatically reduces the size and vascularity of HNSCC tumor xenografts." (PMID 23050142, 2012). "Complementally, SEMA4D, which is under the control of the HIF-family of transcription factors, cooperates with VEGF to promote tumor growth and vascularity in oral squamous cell carcinoma." (PMID 23202951, 2012). "We also observed that a number of genes with tumor suppressor function (GPRC5A, ELF1, NAB2, Sema4D, ACPP, MAP2, RUNX1) persistently remained downregulated in response to radiation exposure." (PMID 23216862, 2012). "With these limitations, we observed that class-3 semaphorins (A–G) and their receptors NRP1/NRP2 as well as SEMA4D and VEGF expressions were heterogeneous between samples, which suggest a differential expression of these genes between tumours." (PMID 18781179, 2008). "MiR-hsa-125b-5p affects cell proliferation, migration, and invasion by targeting multiple tumor suppressor genes such as CD147 and TPD52, and it participates in cancer progression by targeting STAT3, BMPR1B, VEGFA, SphK1, CDKN2A, and Sema4D." (PMID 41361055, 2025). "Combined treatment with anti-Sema4D antibodies and immune checkpoint inhibitors enhances the recruitment of effector lymphocytes and antigen-presenting cells while reducing immunosuppressive populations, leading to effective TME remodeling and tumor rejection." (PMID 41163091, 2025). "Inactivating PLXNB1 has shown a shift in the immune landscape of tumor microenvironments towards an antitumor response; however, angiogenesis is not affected since SEMA4D can bind to alternative receptors." (PMID 40076927, 2025). "Sema4D, also called CD100, is expressed in T cells and tumor tissues." (PMID 37096066, 2023). "SEMA4D was not expressed at higher levels in all tumor types at advanced stages than in early-stage tumors." (PMID 37287907, 2023). "To identify the primary source of SEMA4D in the tumor microenvironment (TME), we conducted a single-cell RNA sequencing (scRNA-seq) transcriptome analysis of 15 independent datasets of 9 tumors with high SEMA4D expression." (PMID 37287907, 2023). "Analysis of TCGA data revealed that SEMA4D was not expressed at higher levels in late stages compared to early stages in all tumor types examined." (PMID 37287907, 2023). "Hence, the purpose of this study was to demonstrate the changes in tumor progression mechanisms such as apoptosis, migration, EMT process, and β-catenin pathway followed by the silencing of SEMA4D expression using siRNA." (PMID 34337054, 2021). "SEMA4D (CD100) binds 3 types of receptors, Plexin-B1 (PLXNB1), Plexin-B2 (PLXNB2), and CD72, which are all expressed by APCs (B cells, monocytes, DCs), endothelial cells, and tumor cells." (PMID 33741032, 2021). "Sema4D is induced by hypoxia through a HIF-1α-dependent mechanism in tumors from different origin such as colon, oral squamous cell and lung carcinoma, with consequent regulation of tumor vascularization." (PMID 33858502, 2021). "Expression of SEMA4D both on mRNA and protein levels was upregulated in ESCC tumor tissues." (PMID 33957921, 2021). "The suppressive role of circ_NRIP1 knockdown in cell growth, migration and invasion in vitro was abated by blocking miR-595; meanwhile, miR-595 overexpression elicited similar anti-tumor role in KYSE30 and KYSE450 cells, which was abrogated by restoring SEMA4D." (PMID 33957921, 2021).